LINC01287 (long independently transcribed non-coding RNA 1287)
Synonyms: TCONS_l2_00027522
Gene: Long non-coding RNA gene on chromosome 7 (153,355,365 to 153,413,985, reverse strand). Ensembl gene ENSG00000234722.
Diseases named in the same sentence as LINC01287 in open-access papers:
LINC01287 is named in the same sentence as 7 diseases in open-access papers, as found by Europe PMC text mining. Sharing a sentence is not in itself a finding about the gene and the disease. The quoted sentences say what the papers report.
breast carcinoma (2 papers, 2021 to 2024). "Overexpression of miR-98 or knockdown of Linc01287 resulted in an inhibitory effect on breast cancer cell progression, highlighting a potential therapeutic pathway in breast cancer treatment." (PMID 38872210, 2024). "We focused on LINC01287 as it ranked the top 25 up-regulated lncRNAs in our study, and previous studies report that LINC01287 acts a role in the tumorigenesis of hepatocellular carcinoma and breast cancer." (PMID 34229645, 2021). "Knockdown of LINC01287 in breast cancer cells inhibits proliferation and metastasis by regulating Wnt/ß-catenin signaling." (PMID 34229645, 2021).
hepatocellular carcinoma (2 papers, 2021). A malignant tumor that arises from hepatocytes. "Virtually, knockdown of LINC01287 upregulates E-cadherin level and reduces N-cadherin and Vimentin levels in hepatocellular carcinoma cells, indicating that LINC01287 is also involved in the EMT of hepatocellular carcinoma." (PMID 34229645, 2021).
colon cancer (1 paper, 2021). "Consistently, we found that LINC01287 promoted proliferation, migration and invasion by regulating miR-4500 in colon cancer cells, while miR-4500 knockdown reversed the effects caused by silencing LINC01287." (PMID 34229645, 2021). "In the present study, high expression of LINC01287 was found to correlate with advanced TNM stage of colon cancer patients." (PMID 34229645, 2021). "Knockdown of LINC01287 inhibited cell growth, colony formation in plates and soft agar, transwell cell migration and invasion, and epithelial-mesenchymal transition (EMT) of colon cancer cells, while LINC01287 overexpression had contrary effects." (PMID 34229645, 2021). "To explore the potential function of LINC01287 in colon cancer, we constructed two LINC01287 shRNA lentivirus (sh-LINC01287–1 and sh-LINC01287–2)." (PMID 34229645, 2021). "Our results also demonstrated an oncogenic role of LINC01287 in colon cancer." (PMID 34229645, 2021). "The expression of LINC01287 in colon cancer cell lines was examined by qRT-PCR." (PMID 34229645, 2021). "However, whether LINC01287 was oncogenic in colon cancer was unknown." (PMID 34229645, 2021). "We also tested the impact of LINC01287 on stemness of colon cancer cells, but unfortunately LINC01287 knockdown showed no influence on the expression levels of stemness markers such as Oct4, Lin28, Nanog and Sox2." (PMID 34229645, 2021).
lung carcinoma (1 paper, 2020). "Result revealed a 6 lncRNA signal, including LINC01287, SNAP25-AS1, LINC00470, AC104809.2, LINC00645 and LINC01010, as an independent prognostic factor for predicting OS in lung cancer patients." (PMID 32518519, 2020).
Stroke (1 paper, 2023). Sudden impairment of blood flow to a part of the brain due to occlusion or rupture of an artery to the brain. "Non-coding genes LINC00870, LINC01206, LINC01287, and LINC02073 are mainly more highly expressed in stroke patients, so they are upregulated." (PMID 37508918, 2023).
tumor (3 papers, 2018 to 2021). "Nevertheless, high LINC01287 expression was significantly associated with tumour size (P = 0.004), lymph node metastasis (P = 0.011) and late clinical stage (P = 0.046)." (PMID 30133116, 2018). "We found that LINC01287 overexpression markedly increased the tumor growth rate, tumor volume and weight compared with EV group." (PMID 34229645, 2021). "In consistence, LINC01287 down‐regulation decreased tumour growth in vivo." (PMID 30133116, 2018). "We then asked whether LINC01287 down-regulation inhibited tumor growth in vivo." (PMID 30001751, 2018).
LINC01287 also shares sentences with these, for which no sentence is quoted: cancer (1 paper).